BRCA1 (BRCA1 DNA repair associated)
Diseases named in the same sentence as BRCA1 in open-access papers (continued):
Sharing a sentence is not in itself a finding about the gene and the disease.
cancer (continued). "Poly (ADP-ribose)-polymerase inhibitors (PARPi) have been approved for cancer patients with germline BRCA1/2 (gBRCA1/2) mutations, and efforts to expand the utility of PARPi beyond BRCA1/2 are ongoing." (PMID 33663560, 2021). "A prospective multicenter MRI screening study in Dutch has demonstrated that the supplemental screening MRI would benefit the early cancer detection and the prognosis in women with BRCA1/2 mutations after an over 9-year follow-up." (PMID 34336698, 2021). "The aza-steroidal alkylators, ASA-A, ASA-B and ASA-C induced a conspicuously higher increase of the PARP1/ACTB mRNA ratio in the UWB1.289 + BRCA1 than in the BRCA1 mutated UWB1.289 cancer cells." (PMID 34440232, 2021). "In a study utilizing multiple-gene panel testing, 23% of breast malignancies in young women were related to germline mutations in known cancer predisposition genes such as BRCA1/2, CHEK2, ATM and PALB2." (PMID 34011307, 2021). "Numerous PARPi’s have been developed, including Olaparib, Rucaparib, Niraparib, Talazoparib, and Veliparib, which are primarily applied in cancer patients with BRCA1/2 mutations." (PMID 34631532, 2021). "Collectively, this review provides an in-depth understanding of the biology and regulatory mechanisms of DDR pathways, highlighting the potential of DDR-associated molecules, particularly BRCA1 and its interconnected partners, in precision cancer medicine." (PMID 34298653, 2021). "Here, we performed a comprehensive analysis for BRCA1/2 variants and associated cancer risk in Korean patients with respect to VUS and PLPVs in BRCA1 and BRCA2." (PMID 34063308, 2021). "In contrast, CIF selected rearrangement signature 3 as the most informative feature, a signature particularly observed in BRCA1-deficient cancers." (PMID 33673506, 2021). "Based on the concept “synthetic lethality”, PARP inhibition can selectively lead to the death of BRCA1- or BRCA2-dysfunction cancer cells in which HR activity is deficient." (PMID 33397362, 2021). "In 2009, Fong et al20 published their results of the first PARPi trial that was enriched for patients with cancer who had BRCA1 and BRCA2 mutations." (PMID 34712892, 2021). "In particular, cytoplasmic mislocalization of BRCA1 is associated with a subgroup of clinically relevant cancer mutations." (PMID 34884734, 2021). "Cancers arising in BRCA1/2 mutations carriers constitute an especial category of malignancies, as they critically change their biological properties over the course of treatment." (PMID 34454564, 2021). "Breast cancer susceptibility gene (BRCA1) belongs a class of tumor suppressor genes with high penetrance that plays an important role in the response to DNA damage (including DNA double-stranded breaks)." (PMID 33987081, 2021). "Family communication about a BRCA1/2 mutation is recommended by numerous national organizations so that blood relatives can learn about and manage their own cancer risk through genetic counseling and testing." (PMID 34565430, 2021). "HR-deficient cancer cells, i.e., BRCA1/2 mutants, are incapable of faithfully repairing such DNA lesions, resulting in cancer cell death." (PMID 34253820, 2021). "Consistently, CDK4/6 inhibitors and PARP inhibitors have been tested in a number of clinical trials for the treatment of cancer cells with compromised DNA repair, e.g., BRCA1/2 mutations." (PMID 33809714, 2021). "To identify effective drug combinations for BRCA-mutated cancer cells with de novo PARPi resistance, we tested the cellular effect of a panel of compounds either alone or in combination with PARPi in BRCA1-mutated HCC1937 and BRCA2-mutated HCT-15 cells." (PMID 33589588, 2021). "In human tumor xenografts, miR-9 has been found to bind to the 3’-UTR of BRCA1 mRNA, downregulate BRCA1 expression, and enhance cancer cell susceptibility to DNA damage." (PMID 34552867, 2021).
cancer (continued). "Variant p.Trp1815Ter in the BRCA1 gene was seen in four unrelated patients, all with a family history of cancer, indicating a possible founder mutation in the Armenian population." (PMID 33558524, 2021). "The success of PARP inhibitors in treating BRCA1/2-mutated tumors has demonstrated the efficacy of cancer-targeted therapy exploiting synthetic lethality." (PMID 33995041, 2021). "This study evaluates the cancer characteristics, family history of cancer, and outcomes of male BRCA1/2 mutation carriers." (PMID 34575694, 2021). "The current study is novel in its relation to COVID-19, however research remains limited regarding the pandemic and its impact on at-risk cancer populations such as those with BRCA1/2 mutations." (PMID 34969949, 2021). "Given this context of BRCA1/2-mutated cancers, an obstacle is posed in creating an effective therapeutic strategy: how do we target the un-targetable?" (PMID 34070674, 2021). "Olaparib was therefore initially developed for the treatment of HR-deficient cancers in patients carrying BRCA1/2 mutation." (PMID 34451901, 2021). "BRCA1 dysfunction sensitizes cancer cells to PARP inhibitors (PARPi) but the underlying mechanism is unclear." (PMID 34789768, 2021). "The cancer risk associated with pathogenic BRCA1 variants peaks between 30 and 50 years, with a standardised incidence rate of 46.2 (37.3–57.1)% between the ages of 31 and 40 years compared to 7 (4.5–11)% in those between 61 and 70 years." (PMID 34771713, 2021). "Here, we report for the first time a major effect of BRCA1 haploinsufficiency on tumor-associated stroma in the context of BRCA1-associated cancers." (PMID 33513753, 2021). "BRCA1 is a tumor suppressor gene that participates in DNA repair processes; mutations therein elevate the risk of developing breast, ovarian, and other cancers." (PMID 34195081, 2021). "For both groups, P/LP variants were identified in genes that are associated with heritable CRC and in genes associated with other known cancer syndromes, such as BRCA1 and BRCA2 in HBOC." (PMID 34585040, 2021). "Dysfunction of the BRCA1 pathway enhances the therapeutic efficiency of poly-(ADP-ribose) polymerase inhibitors (PARPi) in cancers, but the molecular mechanisms underlying this sensitization to PARPi are not fully understood." (PMID 34789768, 2021). "Since the successful use of the PARP1 inhibitor olaparib in the treatment of cancers caused by BRCA1 and BRCA2 mutations, such as breast, ovarian, pancreatic, and prostate cancers, synthetic lethality-based anticancer therapy has garnered enormous attention." (PMID 34583722, 2021). "Due to elevated risk of cancer, BRCA1/2 mutation carriers are increasingly encouraged to undergo RRBSO after completion of childbearing." (PMID 33885953, 2021). "Disruptive mutations in HRR have been shown to enhance the sensitivity of BRCA1/2‐mutated cancer cells to PARP inhibitors." (PMID 34761497, 2021). "BRCA1/BRCA2 PV associated cancers were smaller overall with 75.0% and 85.4% being ≤ 20 mm respectively, potentially reflecting MRI screening in these groups." (PMID 34312777, 2021). "This literature review addresses cancer predisposition genes, including BRCA1, BRCA2, and PALB2, synthetic lethality in the context of DNA repair machinery, as well as available treatment options." (PMID 34070674, 2021). "Many patients with these specific cancer subtypes harbor somatic mutations in BRCA1 or BRCA2, or other homologous recombination (HR) genes, which inspired the development of targeted therapeutics." (PMID 33784323, 2021). "The involvement of the BRCA1/2 genes in cancer pathogenesis is assumed to be associated with their role in maintaining genomic stability in DNA repair, cell cycle regulation, and apoptosis." (PMID 33671579, 2021). "For example, mothers who are BRCA1/2 carriers are often keenly interested in knowing their children’s cancer risk, especially those presenting for testing out of concern for their children’s future health." (PMID 34565430, 2021).
cancer (continued). "Germline mono-allelic mutations in the tumor suppressor genes BRCA1/2 (breast cancer susceptibility gene 1/2) predispose to breast and ovarian cancer, and in the case of BRCA2, also confer moderate risk to other cancers such as pancreatic and prostate cancer." (PMID 34359619, 2021). "Compared to other models, this tool allows the incorporation of genotypes related to other cancer susceptibility genes which include BRCA1 and BRCA2, as well as family history, reproductive risk factors and ductal atypical hyperplasia." (PMID 34771713, 2021). "Our results indicate that the simultaneous inhibition of RAD52-mediated DNA repair with the induction of DSBs appears to exaggerate the cytotoxicity of mitoxantrone and doxorubicin in BRCA1-deficient cancer cell lines." (PMID 33784323, 2021). "Other examples include cancer susceptibility genes such as BRCA1 and BRCA2 that occur more commonly in Ashkenazi Jewish populations." (PMID 33842350, 2021). "The risk of prostate cancer in male carriers of BRCA1 variants is approximately equivalent to the general population’s risk, but the phenotype of such cancers, as well as the therapeutic approach, is similar to that of carriers of BRCA2 variants." (PMID 34771713, 2021). "A class of drugs called PARP inhibitors, which block the repair of DNA damage, have been found to arrest the growth of cancer cells that have pathogenic BRCA1 or BRCA2 variants." (PMID 34207450, 2021). "The BRCAPRO model was developed in the setting of women undergoing genetic counseling and uses a detailed family history of breast and other cancers to estimate risk both of a BRCA1/2 mutation and risk of breast cancer." (PMID 35008209, 2021). "N = 101 BRCA1/2 mutation carriers answered self-report questionnaires on illness representations, coping strategies, cancer worry and depressive symptoms." (PMID 34069035, 2021). "Although most BRCA1-deficient cancers respond to DNA-damaging agents, resistance and tumor recurrence remain a challenge to survival outcomes for BLBC patients." (PMID 33478572, 2021). "Some of the PARP inhibitors have already been approved to treat cancers with germline mutations in the BRCA1 and BRCA2 genes." (PMID 34638660, 2021). "Several PARPi (e.g., Olaparib, Rucaparib, Talazoparib, and Niraparib) have been approved as monotherapy for either breast, ovarian or both cancers associated with BRCA1/2 germline mutations or HR-deficiency." (PMID 35008272, 2021). "In recent years, the introduction of poly (ADP-ribose) polymerase-inhibitors (PARPi) has significantly increased treatment options in cancers harboring BRCA1/2 mutations." (PMID 34202525, 2021). "The National Comprehensive Cancer Network (NCCN) recommends that BRCA1 mutation-positive women undergo periodic breast screening and consider mastectomy and salpingo-oophorectomy to reduce their cancer risk." (PMID 33767581, 2021). "The synthetic lethality between RAD52 and BRCA1/2 has long been established, identifying RAD52 as a potential therapeutic target against cancers with BRCA1/2 gene mutations." (PMID 33995041, 2021). "A prospective cohort study of BRCA1/2 cancer-free mutation carriers also reported that the relative risk of developing cancer varies with the location of the mutation (BCCR, OCCR)." (PMID 32862296, 2021). "PARP inhibitors sensitize cancer cells to both chemo- and radio-therapy and BRCA1/2-deficient cells are 1000 times more sensitive to PARP inhibitors than wild-type cells." (PMID 33498525, 2021). "Cancer cells with mutations that prevent homologous recombination repair, such as BRCA1/2 loss-of-function mutations, are often synthetically lethal with PARPi due to significantly lower DNA damage response." (PMID 38107772, 2021).
cancer (continued). "As a result, targeting DDX11 confers improved chemotherapy responsiveness in both chemotherapy-sensitive and drug-resistant BRCA1/2-mutated cancers that regained homologous recombination proficiency by suppressor mutation or somatic reversion." (PMID 33879618, 2021). "Many women with a BRCA1/2 mutation overestimate their risk of developing cancer in the coming years." (PMID 34069035, 2021). "In contrast, ASHRA clearly detected the intermediate HR activity of BRCA1-R1699Q and -V1736A, which was associated with intermediate sensitivity to olaparib and cancer risk." (PMID 36860287, 2021). "As a result, DDX11 down-regulation aggravates the chemotherapeutic sensitivity of BRCA1/2-mutated cancers and resensitizes chemotherapy drug–resistant BRCA1/2-mutated cancer cells that regained homologous recombination proficiency." (PMID 33879618, 2021). "Evidence for the role of specific genetic factors conferring risk for these cancers culminated with the discoveries of BRCA1 and BRCA2, the BC and OC cancer predisposing genes." (PMID 34298626, 2021). "Higher responses were evident in ATM-deficient cancers for the carboplatin group, and in BRCA1/2-mutated cancers for the olaparib-treated group where responses were independent of ATM status." (PMID 33672884, 2021). "Pathogenic or likely pathogenic mutations in BRCA1/2, mismatch repair and other cancer predisposing genes are found in many cancers for which genetic association studies are not available, leaving the causal role of mutations open." (PMID 34503195, 2021). "Though 42 different pathogenic BRCA1 or BRCA2 variants have been identified in FC cancer families of Quebec, five recurrent pathogenic variants account for 84% of all mutation-positive BC and/or OC families." (PMID 34861889, 2021). "In fact, BRCA1 mutations culminate in DNA repair defects that can render cancer cells more vulnerable to therapy." (PMID 34298653, 2021). "Determining the precise effects of the SNPs in BRCA1 and BRCA2 mutation carriers will provide insights for understanding the biological basis of cancer development associated with BRCA1 and BRCA2 mutations." (PMID 33597508, 2021). "In the prospective cohort GENEPSO, which aims at assessing environmental and lifestyle risk factors, BRCA1/2 mutation carriers are followed over time to observe characteristics of subjects who are developing either primary or secondary cancer." (PMID 34325649, 2021). "As PARPi is used in cancer with BRCA1/2 mutations which are defective in HR, upon inhibition, cells must revert to the error-prone NHEJ or cause replication fork stalling." (PMID 33498235, 2021). "Because DSB repair pathways are impaired with BRCA1 mutation, BRCA1-mutant cancers are significantly more sensitive to cisplatin treatment." (PMID 34360968, 2021). "The best-known examples of cancer predisposition genes are the tumor suppressors BRCA1 and BRCA2 involved in breast and ovarian cancers." (PMID 34290314, 2021). "Cancers with BRCA1/2 loss and other accumulation of similar genomic scars resulting in HRD displayed increased sensitivity to chemotherapy." (PMID 34869593, 2021). "There are some established biomarkers that can be used to identify patients with a higher cancer risk and that are suitable for PARPi, like BRCA1/2." (PMID 34712892, 2021). "Although the efficacy of contralateral RRM for women with BRCA1/2 mutation has been controversial, many studies have suggested a marked decrease of cancer in the opposite breast." (PMID 34285295, 2021). "As shown, BC is the most frequent cancer, confirming that the BC risk in BRCA1 and BRCA2 mutation carriers is 45–80%." (PMID 33484353, 2021).
cancer (continued). "In the present study, 35% of PABC patients tested carried pathogenic mutations in two known cancer predisposition genes (BRCA1 and CHEK2)." (PMID 34011307, 2021). "Regaining HR and fork protection by inactivation of 53BP1, RIF1, REV7, or a Shieldin, and PTIP, respectively, results in resistance to PARPi in BRCA1-deficient cancer cells." (PMID 33784323, 2021). "These tissue type-specific associations are explained by the correlation of BRCA1 mRNA expression with different genes in these cancers." (PMID 34966485, 2021). "Nowadays, reports state that BRCA1/2 mutations account for only approximately 50% of the identifiable germline cancer predisposition variants in BC patients." (PMID 34011307, 2021). "Detection of founder/recurrent variants in the majority (74%) of SA patients justified the use of a first-tier assay to select patients eligible for NGS of the BRCA1/2 or other cancer susceptibility genes." (PMID 34660253, 2021). "Molecular subtyping of the tumors demonstrated that majority of the tumors are basal-like, while other subtypes also exist, which is similar to human BRCA1-deficient cancers." (PMID 34815798, 2021). "BRCA1- and 2-mutated cancers are incredibly sensitive to PARP inhibitors and Pol θ knockdown, suggesting a reliance on MMEJ." (PMID 34830134, 2021). "Across cancer types, only 89% of patients with a germline BRCA1 variant and 79% of patients with a BRCA2 variant have a tumor with complete loss of the wild-type allele." (PMID 34067105, 2021). "Patient received genetic counseling because of family history of cancers, and results returned positive in April 2017 showing a deleterious BRCA1 germline mutation (BRCA1 p.His1006Glnfs*17.c.3018_3021delTTCA) that motivated the use of PARPi." (PMID 33888155, 2021). "Despite the increased risk conferred by BRCA1 mutations to cancer onset, pre-clinical and clinical data have ascertained that BRCA1 impairment is commonly associated with chemosensitivity in cancer cells." (PMID 34298653, 2021). "Most VUSs in BRCA1/2 are missense variants, which have uncertain influences on the function of the protein product and the cancer risk of the carrier in question." (PMID 35087763, 2021). "In November 2020, the FDA approved the next-generation sequencing (NGS)-based FoundationOne Liquid CDx test that uses cf-DNA isolated from plasma of cancer patients for use in mCRPC to identify mutations on the BRCA1, BRCA2 and ATM genes." (PMID 34830878, 2021). "More recently, this inhibition was also shown to have antitumor activity with limited adverse side effects in cancer patients with BRCA1 or BRCA2 mutations." (PMID 34359565, 2021). "In cancers that contain loss-of-function mutations in BRCA1 and BRCA2, back-up DNA repair pathways exist." (PMID 34950659, 2021). "While a cell with an intact homologous recombination (HR) pathway can repair these DSB effectively, olaparib causes synthetic lethality in HR deficient tumor cells, such as in BRCA1/2-mutated cancers." (PMID 34451901, 2021). "Clinically, we would expect that surviving patients who are compound heterozygous for deleterious mutations in BRCA1 would have showed an early manifestation of prominent FA features, such as anemia, infection tendency and cancer development." (PMID 33477375, 2021). "PARPi causes unrepaired accumulation of single-strand DNA breaks, which eventually culminate into double-strand breaks, causing the death of the BRCA1/2-mutant cancer cells." (PMID 38107772, 2021).